H4C4 (H4 clustered histone 4)
Description:
Core component of nucleosome. Nucleosomes wrap and compact DNA into chromatin, limiting DNA accessibility to the cellular machineries which require DNA as a template. Histones thereby play a central role in transcription regulation, DNA repair, DNA replication and chromosomal stability. DNA accessibility is regulated via a complex set of post-translational modifications of histones, also called histone code, and nucleosome remodeling.
Synonyms: H4/B; H4FB; HIST1H4D; dJ221C16.9
Target class: Other nuclear protein
Gene: Protein-coding gene on chromosome 6 (26,188,710 to 26,189,112, reverse strand). Ensembl gene ENSG00000277157.
Subcellular location: Nucleus; Chromosome
Pathways (Reactome):
Gene expression (Transcription): B-WICH complex positively regulates rRNA expression; DNA methylation; ERCC6 (CSB) and EHMT2 (G9a) positively regulate rRNA expression; MLL4 and MLL3 complexes regulate expression of PPARG target genes in adipogenesis and hepatic steatosis; NoRC negatively regulates rRNA expression; PRC2 methylates histones and DNA; RNA Polymerase I Promoter Escape; RNA Polymerase I Promoter Opening; RUNX1 regulates genes involved in megakaryocyte differentiation and platelet function; RUNX1 regulates transcription of genes involved in differentiation of HSCs; Regulation of endogenous retroelements by KRAB-ZFP proteins; Regulation of endogenous retroelements by Piwi-interacting RNAs (piRNAs); Regulation of endogenous retroelements by the Human Silencing Hub (HUSH) complex; SIRT1 negatively regulates rRNA expression; Transcriptional regulation by small RNAs
Chromatin organization: CHD1 and CHD2 subfamily; CHD6, CHD7, CHD8, CHD9 subfamily; ChAHP complex assembly; HATs acetylate histones; HDACs deacetylate histones; HDMs demethylate histones; Interaction of NuRD complexes with transcription factors; NuRD complex assembly; PKMTs methylate histone lysines; RMTs methylate histone arginines
DNA Repair: Cleavage of the damaged purine; Cleavage of the damaged pyrimidine; Nonhomologous End-Joining (NHEJ); Processing of DNA double-strand break ends; Recognition and association of DNA glycosylase with site containing an affected purine; Recognition and association of DNA glycosylase with site containing an affected pyrimidine; Recruitment and ATM-mediated phosphorylation of repair and signaling proteins at DNA double strand breaks
Cell Cycle: Condensation of Prophase Chromosomes; Deposition of new CENPA-containing nucleosomes at the centromere; G2/M DNA damage checkpoint; Inhibition of DNA recombination at telomere; Packaging Of Telomere Ends
Developmental Biology: Activation of anterior HOX genes in hindbrain development during early embryogenesis; Chromatin modifications during the maternal to zygotic transition (MZT); Replacement of protamines by nucleosomes in the male pronucleus
and 20 more pathways
Gene Ontology:
Molecular function: protein binding; RNA binding; structural constituent of chromatin; DNA binding; protein heterodimerization activity
Biological process: negative regulation of megakaryocyte differentiation; nucleosome assembly; chromatin organization; protein localization to CENP-A containing chromatin; telomere organization
Cellular component: CENP-A containing nucleosome; chromosome, telomeric region; extracellular exosome; membrane; nucleoplasm; nucleosome; nucleus; protein-containing complex; extracellular region; chromosome
Genetic constraint (gnomAD): Loss-of-function variants: 8 observed, 4.66 expected, observed/expected ratio (o/e) 1.72, 90% interval 0.91 to 1.95. That is too few expected variants to judge how well the gene tolerates losing a copy. Missense variants: 223 observed, 159.82 expected, observed/expected ratio (o/e) 1.4, 90% interval 1.25 to 1.56. Synonymous variants: 130 observed, 60.46 expected, observed/expected ratio (o/e) 2.15.
Homologues: Orthologues: rabbit H4C1 (100% identical), tropical clawed frog h4c3 (100% identical). Paralogues in human: H4C1 (100% identical), H4C11 (100% identical), H4C12 (100% identical), H4C13 (100% identical), H4C14 (100% identical), H4C15 (100% identical), H4C16 (100% identical), H4C2 (100% identical), H4C3 (100% identical), H4C5 (100% identical), H4C6 (100% identical), H4C8 (100% identical), and 2 more.